ARRB2 (arrestin beta 2)
Diseases named in the same sentence as ARRB2 in open-access papers (continued):
Sharing a sentence is not in itself a finding about the gene and the disease.
ARRB2 also shares sentences with these, for which no sentence is quoted: Obesity (4 papers); Insulin resistance (2); leukemia (2); neurological diseases (2); adenocarcinoma (1); Aicardi-Goutierès syndrome (1); atherosclerosis (1); cardiac arrhythmia (1); cardiac insufficiency (1); cardiac ischemia (1); cervical cancer (1); cervical squamous cell carcinoma (1); depression (1); diabetes (1); endometrial carcinoma (1); epilepsy (1); glioblastoma (1); Hepatic steatosis (1); infectious disease (1); inflammation (1); intestinal tumors (1); intrahepatic cholangiocarcinoma (1); ischemia reperfusion injury (1); lung squamous cell carcinoma (1); medulloblastoma (1); melanoma (1); metabolic disorders (1); non-small cell lung carcinoma (1); Pan (1); pancreatic cancer (1).
A further 7 diseases each share a sentence with ARRB2 in 1 paper.